CRP (C-reactive protein)
Diseases named in the same sentence as CRP in open-access papers (continued):
Sharing a sentence is not in itself a finding about the gene and the disease.
respiratory disease (continued). "In association with selenium, some authors reported an inverse correlation between selenium and C-reactive protein in patients with respiratory diseases." (PMID 29875918, 2018). "From the literature point of view, an inverse correlation between selenium and C-reactive protein in patients with respiratory diseases was found." (PMID 29875918, 2018). "However, because CRP levels are also elevated in various non-respiratory diseases, it is necessary to make a comprehensive diagnosis in conjunction with other tests." (PMID 38250933, 2024). "Luminex-based analysis of HIV-negative individuals from sub-Saharan African countries for prespecified analytes has identified a 2-protein panel and a 9-protein panel, both including CRP, that distinguish TB from other respiratory diseases, with comparatively high sensitivity, but lower specificity." (PMID 38512356, 2024). "Subsequent studies could consider both a broader repertoire of diagnoses (e.g., skin or respiratory diseases) as well as objective health status indicators (such as C-reactive protein levels in RA patients)." (PMID 35270828, 2022). "Using the same variables in the model, that is, both individual characteristics and reported non‐respiratory diseases, no independent associations were found between having a non‐respiratory disease, and FeNO or CRP levels." (PMID 34123365, 2021). "In spite of the correlation with B‐Eos and being well‐known and widely used in population‐based studies as a marker of systemic inflammation, CRP did not independently associate with non‐respiratory diseases in our study, whereas B‐Eos count did." (PMID 34123365, 2021). "Furthermore, the median levels of CRP were only significantly different for patients with diseases of the respiratory system (U = 578,5, z = −2.171, p = 0.030)." (PMID 34830693, 2021). "A negative association between selenium and C-reactive protein was found in some illnesses including inflammatory and respiratory diseases." (PMID 29875918, 2018). "High CRP levels were reported sensitive and specific to determine lower respiratory diseases." (PMID 23497669, 2013). "Likewise serum levels of the marker of acute inflammation C-reactive protein (CRP) in otherwise healthy subjects are associated with a similar range of diseases and outcomes but also include smoking related respiratory disease." (PMID 23391158, 2013). "Although a relationship between increased CRP and deaths from respiratory disease has not been comprehensively proven, high CRP is associated with a yearly decrease in forced expiration volume of sustained smokers." (PMID 19732183, 2009). "The pooled results suggested that compared with conventional biomedical therapy alone, Shufeng Jiedu Capsule combined with biomedical therapy may reduce CRP levels in patients with respiratory diseases presenting with wind-heat syndrome (SMD = −0.99, 95% CI -1.55 to −0.43, P = 0.0005)." (PMID 41050407, 2025). "Similarly, a low serum KL-6 level (≤ 436 U/mL) with a high CRP level was also associated with non-ILD respiratory disease or non-severe TR-ILD rather than severe TR-ILD (OR: 0.41, 95% CI: 0.18–0.98; p = 0.045)." (PMID 37872370, 2023). "During the Guangzhou Asian games, diminished air pollution was associated with reduced hospital admissions (for non-accidental, cardiovascular, and respiratory diseases), as well as an acute reduction in CRP and fibrinogen associated with systemic inflammation in COPD." (PMID 30893301, 2019). "At the same time, they were the only ones to identify C-reactive protein (CRP), neutrophil count, presence of muscoskeletal-, hypertensive- or respiratory disease, denture use, and BP medication use, as important in women." (PMID 41267842, 2025). "Receiver operating characteristics analyses using a 5-protein panel (CFHR5, LRG1, CRP, LBP, and SAA1) exhibited discriminatory power in distinguishing TB from other respiratory diseases (AUC = 0.81)." (PMID 32780727, 2020).
respiratory disease (continued). "Respiratory disease is most prevalent during OOH services, and in more than 50 % of the consultations, a CRP test is performed." (PMID 26585447, 2015). "PCT was found very useful to assess the severity of respiratory disease and the necessity of antibiotic use as CRP in various studies, and it has been reported that PCT is a more sensitive marker than CRP." (PMID 23497669, 2013). "Analysis of the correlations between CRP, neutrophil count, and microbial species related to respiratory disorders in the patients showed that neither of them correlated with the bacterial species." (PMID 35346147, 2022). "In both children/adolescents and adults, B‐Eos count and FeNO were higher in those with respiratory disease, while CRP levels were not significantly different in the two age groups." (PMID 34123365, 2021). "Notably, CRP and HGB, Ferritin and LDH, and other biomarker pairs showed statistically significant correlations that align with known inflammatory and metabolic pathways, further validating their role in respiratory disease progression." (PMID 41395368, 2025). "Non‐respiratory diseases influence B‐Eos count but not FeNO or CRP." (PMID 34123365, 2021). "In addition, dogs with other airway diseases such as upper respiratory diseases may not experience a rise in CRP at all (e.g., rhinitis)." (PMID 36290272, 2022). "This is in accordance with previous reports showing elevated inflammatory markers (eg, CRP, IP-10, IFN-γ, CCL1, and VEGF) in unstimulated plasma or serum in active TB compared to LTBI or other respiratory diseases regardless of HIV-1 status." (PMID 36998631, 2023). "A high serum KL-6 level was an independent risk factor for severe TR-ILD, and a low serum KL-6 level with a high PCT or CRP level could exclude the diagnosis of severe TR-ILD, rather favoring non-ILD respiratory disease or non-severe TR-ILD." (PMID 37872370, 2023).
hematological malignancies (66 papers, 2012 to 2026). "During treatment, systemic symptoms such as fever, malaise, joint pain, and loss of appetite emerged, and blood tests showed elevated C-reactive protein and soluble interleukin-2 receptor levels, suggesting suppurative lymphadenitis or hematologic malignancy." (PMID 39569307, 2024). "Concurrent hematological disorders, high preoperative CRP levels, and short specimen resection were associated with an increased risk of reoperation in patients with iBD who underwent their initial bowel resection." (PMID 39597915, 2024). "Age; screening for medical reasons; higher SOFA score; solid tumor; hematologic malignancy; and higher T-bilirubin, lactate, and CRP levels were associated with in-hospital mortality in this study." (PMID 35114944, 2022). "CRP has been mostly investigated to be associated with VCZ C0 in hematologic malignancy and solid organ transplant patients (42–62 years), and CRP levels are the main risk factor for VCZ overdose in French hematological patients." (PMID 35462904, 2022). "The objective of this study was to investigate diagnostic values of PCT and CRP in predicting systemic bacterial infection in patients with hematologic malignancies." (PMID 31821331, 2019). "They concluded that a metabolic profile characterized by an increased BMI in conjunction with increased serum C-reactive protein (CRP) and cystatin C levels may predict an elevated risk of hematologic malignancies in middle age and older people." (PMID 38159164, 2024). "In conclusion, we currently observe the kinetic changes of IL‐6, PCT, and CRP to investigate their role in initial antibiotic efficacy evaluation of FN patients with hematological disorder, confirming IL‐6 and CRP as the biomarkers." (PMID 38967137, 2024). "This study confirmed IL‐6 and CRP levels, and the percentage change in IL‐6 as the biomarkers for initial antibiotic efficacy prediction in hematological disorder patients with FN." (PMID 38967137, 2024). "In the current study, an accompanying hematological disorder, elevated CRP levels before initial surgery, and a longer specimen resection length were significantly associated with reoperation in patients with iBD." (PMID 39597915, 2024). "This study aims to investigate the early kinetics of interleukin 6 (IL‐6), procalcitonin (PCT), and C‐reactive protein (CRP) on initial antibiotic efficacy in hematological disorder patients with febrile neutropenia (FN)." (PMID 38967137, 2024). "CRP has been reported to be a prognostic indicator in a variety of hematologic malignancies and solid tumors." (PMID 36441359, 2023). "The results were consistent with those of previous studies, in which the correlation coefficient between PCT and CRP was 0.460 in patients with hematologic malignancies, and between CRP and SAA, it was 0.682 in patients with septic shock." (PMID 37046430, 2023). "C-reactive protein (CRP), an inflammatory marker, documented to be significantly increased in hematological malignancies was seen in three patients (cases 1, 2, and 3)." (PMID 35308495, 2022). "In concurrence with results from previous studies on hematological malignancies, univariate analysis revealed CRP and albumin as individual components of the GPS and CAR to have significant impact on OS (p < 0.0001; p < 0.0001)." (PMID 34415426, 2022). "The combination of C-reactive protein (CRP) and the MASCC model was successful in assessing the mortality risk of patients with FN and hematological malignancies." (PMID 33299642, 2020). "Given that C-reactive protein (CRP) is a commonly used biomarker in hematologic malignancies." (PMID 41601642, 2026). "Herein, we conducted a prospective study to investigate whether IL‐6, PCT, and CRP can be used to evaluate initial antibiotic efficacy of FN patients with hematological disorder through observing the early kinetic changes in these three biomarkers." (PMID 38967137, 2024).
hematological malignancies (continued). "Therefore, this study aimed to evaluate and compare the diagnostic and prognostic performance of PCT, DNI, CRP, and SAA in patients with hematologic diseases." (PMID 37046430, 2023). "Several reports showed that high CRP levels are significantly associated with higher non-relapse mortality and poor OS in patients with hematological malignancies treated with HSCT17–19." (PMID 35614177, 2022). "Furthermore, CRP and white blood cell counts can serve as a dual prognostic predictor in solid tumors and hematological malignancies." (PMID 32707721, 2020). "Thus, the objective of the present study was to retrospectively analyze 614 febrile episodes that developed in patients with hematologic malignancies and investigate diagnostic values of PCT and CRP in predicting systemic bacterial infection." (PMID 31821331, 2019). "Inflammatory-nutritional markers including the modified Glasgow Prognostic Score (mGPS), the CRP × fibrinogen/albumin ratio (CFA) and the C-reactive protein-albumin ratio (CAR) are closely associated with prognosis in patients with various solid tumors and some hematological malignancies." (PMID 41586228, 2025). "Meanwhile, the CRP + NLR score devised in this study may be easier to use than the LRINEC score because it is less susceptible to the influence of certain pathological conditions, except for hematological diseases." (PMID 36503406, 2022). "Conversely, in patients with non-haematological disease, the Anelloviridae-positive group showed significantly higher HBG levels and significantly lower CRP and RBC levels (P < 0.05)." (PMID 39044261, 2024). "In the present study, we evaluated PCT, DNI, CRP, and SAA levels in serum samples from 127 patients with hematologic diseases." (PMID 37046430, 2023). "After removing children with hematological malignancies, the CPSS group still had higher levels of PCT and CRP than the CNSS group." (PMID 36313890, 2022). "The results of laboratory data showed that ALT, AST, CRP, and LDH tests have increased in COVID‐19 patients with hematological malignancies." (PMID 35385130, 2022). "Six patients were diagnosed by routine test without any symptoms, one patient was neonate and five had hematological malignancy, half of them had normal CRP level and white blood cell counts." (PMID 39075343, 2024). "Conversely, a retrospective study including 61 pediatric patients (mean age 10.3 years; >75% affected by hematological disease, 50% of whom were undergoing HCT) found by multivariate analysis that a CRP level < 110 mg/L was an independent predictor of low voriconazole Cmin < 1.0 mg/L (p = 0.045)." (PMID 39065156, 2024). "The C-reactive protein-albumin-lymphocyte (CALLY) index, integrating markers of inflammation, nutritional status, and immune competence, has demonstrated prognostic relevance in solid tumors; however, its relevance in hematologic malignancies remains unexplored." (PMID 41827779, 2026). "In our multivariable logistic regression model, a lactate concentration > 6 mmol/l was the only independent predictor of ICU death; age, sex, HScore, CCI, CRP, AST, ferritin, vasopressor use, immunosuppression, and haematologic disease were not significant." (PMID 41234904, 2025). "Conversely, in patients without haematological disease, the positive group exhibited significant increases in ALC, HBG, and CRP levels and a significant decrease in RBC levels (P < 0.05)." (PMID 39044261, 2024). "Among patients with non-viral pathogens, the positive group of patients with haematological disease showed significant increases in ALC, HBG, CRP, and PCT levels, whereas ANC and RBC counts were significantly lower (P < 0.05)." (PMID 39044261, 2024). "In patients without haematological disease, the positive group showed significant increases in ALC, HBG, CRP, and PCT levels, while the RBC count was significantly lower (P < 0.05)." (PMID 39044261, 2024).
hematological malignancies (continued). "In patients with haematological disorders, we observed a significant increase in ANC in the Anelloviridae-positive group compared to the negative group, while ALC, HBG, CRP, and PCT levels were significantly lower (P < 0.05)." (PMID 39044261, 2024).
neurodegenerative disease (58 papers, 2013 to 2025). A disorder of the central nervous system characterized by gradual and progressive loss of neural tissue and neurologic function. "CRP and homocysteine serve as risk and prognostic factors for cardiovascular, metabolic and neurodegenerative diseases, among others." (PMID 40033138, 2025). "Studies have shown that an increase in LPC levels is associated with cardiovascular and neurodegenerative diseases, and some LPCs are negatively correlated with C-reactive protein increasing with age." (PMID 39997731, 2025). "Homocysteine, uric acid, Cys C, and CRP are implicated in the pathogenesis and progression of degenerative diseases." (PMID 38459662, 2024). "C-reactive protein (CRP) has previously been associated with neurodegenerative diseases and poor cognitive outcomes in normal aging." (PMID 36119691, 2022). "Physiologically, CRP levels exhibit stability and lack diurnal variations, indicating its potential as a reliable measure in clinical settings to examine brain vasculature changes associated with neurodegenerative diseases." (PMID 39610697, 2024). "Associated with other biomarkers, CRP might be useful for monitoring the development of neurodegenerative diseases." (PMID 38891863, 2024). "Though the precise mechanisms by which CRP interacts with immune cells and pro-inflammatory molecules are still not clearly understood, its involvement in neurodegenerative disease progression is well documented." (PMID 40534869, 2025). "This review explores the complex interplay between CRP, encompassing its isoforms pCRP, pCRP*, and mCRP, and misfolded proteins, examining the specific contributions to inflammation and neurodegenerative disease pathogenesis." (PMID 40534869, 2025). "CRP is known as a biomarker for acute inflammation but is also involved in chronic inflammation state of neurodegenerative diseases." (PMID 39610697, 2024). "Third, elevated CRP levels can also be observed in patients with chronic inflammatory and neurodegenerative diseases." (PMID 36079002, 2022). "Further, ALS is a neurodegenerative disease commonly in middle age population and patients in those age group often suffer from other comorbid condition, can influence CRP level." (PMID 35201675, 2022). "Previous studies have demonstrated that C-reactive protein (CRP) and glycated hemoglobin (HbA1c) levels are independently associated with neurodegenerative diseases, which can be improved by altering dietary patterns." (PMID 35252292, 2022). "An inverse relationship between the creatinine level and MS has been recently reported and serum levels of CRP and creatinine have been proposed as potential biomarkers for neurodegenerative diseases." (PMID 34287336, 2021). "Research has shown that in the elderly, increased levels of serum inflammatory factors such as tumour necrosis factor-α (TNF-α), interleukin-6 (IL-6) and C-reactive protein (CRP) are considered to be risk factors of cardiovascular and degenerative diseases." (PMID 34925376, 2021). "Our results show that suPAR is more specific than CRP whereas CRP is more sensitive than suPAR for discrimination of vertebral osteomyelitis and degenerative diseases of the spine." (PMID 31727136, 2019). "Moreso, our study demonstrated that improvement in the diagnostic power for discrimination of vertebral osteomyelitis and degenerative diseases of the spine can be achieved by a combination of both suPAR and CRP." (PMID 31727136, 2019). "Animal models and patients with neurodegenerative diseases had higher levels of IL-6 and CRP, providing evidence that peripheral inflammatory mediators can increase ROS production and also interfere with neurocognitive functions." (PMID 27081392, 2016). "Our results found AQR, ZNF587B, CRP, and PAGIn have been accumulated in AD patients as well as been reported associated with neurodegenerative diseases, while their relationship with AD has not been thoroughly examined." (PMID 38605603, 2024).